MT-RNR1 (mitochondrially encoded 12S rRNA)
Description:
Regulates insulin sensitivity and metabolic homeostasis. Inhibits the folate cycle, thereby reducing de novo purine biosynthesis which leads to the accumulation of the de novo purine synthesis intermediate 5-aminoimidazole-4-carboxamide (AICAR) and the activation of the metabolic regulator 5'-AMP-activated protein kinase (AMPK). Protects against age-dependent and diet-induced insulin resistance as well as diet-induced obesity. In response to metabolic stress, translocates to the nucleus where it binds to antioxidant response elements (ARE) present in the promoter regions of a number of genes and plays a role in regulating nuclear gene expression in an NFE2L2-dependent manner and increasing cellular resistance to metabolic stress. Increases mitochondrial respiration and levels of CPT1A and cytokines IL1B, IL6, IL8, IL10 and TNF in senescent cells. Increases activity of the serine/threonine protein kinase complex mTORC2 and reduces activity of the PTEN phosphatase, thus promoting phosphorylation of AKT. This promotes AKT-mediated phosphorylation of transcription factor FOXO1 which reduces FOXO1 activity, leading to reduced levels of MSTN and promotion of skeletal muscle growth. Promotes osteogenic differentiation of bone marrow mesenchymal stem cells via the TGFB/SMAD pathway. Promotes osteoblast proliferation and osteoblast synthesis of type I collagens COL1A1 and COL1A2 via the TGFB/SMAD pathway.
Synonyms: 12S; MOTS-c; formerly MTRNR1
Gene: Mitochondrial ribosomal RNA gene on chromosome MT (648 to 1,601, forward strand). Ensembl gene ENSG00000211459.
Subcellular location: Secreted; Mitochondrion; Nucleus
Pathways (Reactome):
Metabolism of RNA: FASTK family proteins regulate processing and stability of mitochondrial RNAs; Mitochondrial RNA degradation; rRNA modification in the mitochondrion; rRNA processing in the mitochondrion; tRNA processing in the mitochondrion
Metabolism of proteins: Mitochondrial ribosome-associated quality control; Mitochondrial translation elongation; Mitochondrial translation initiation; Mitochondrial translation termination
Gene-disease validity (ClinGen):
ClinGen rates the evidence that MT-RNR1 causes each of these diseases.
mitochondrial disease (mitochondrial): Definitive.
Diseases named in the same sentence as MT-RNR1 in open-access papers:
MT-RNR1 is named in the same sentence as 87 diseases in open-access papers, as found by Europe PMC text mining. Sharing a sentence is not in itself a finding about the gene and the disease. The quoted sentences say what the papers report.
deafness (30 papers, 2010 to 2025). An inherited or acquired condition characterized by the complete loss of the ability to hear from one or both ears. "MTRNR1 has previously been linked to auditory neuropathy spectrum disorder and deafness and is associated with mitochondrial dysfunction." (PMID 37938766, 2024). "Five had variants in the MT‐RNR1 gene which are associated with non‐syndromic or aminoglycoside‐induced deafness." (PMID 39095335, 2024). "Among the mutations in the MT-RNR1 gene associated with the development of deafness, the most common is an m1555A>G transition." (PMID 38543117, 2024). "In the present study, 2D-PCR was used to detect the GJB2, SLC26A4, GJB3, and MT-RNR1 genes in 116 deaf patients and to explore the diagnosis rate and mutation patterns of four common pathogenic genes for deafness in Changzhou, Jiangsu, China." (PMID 38172427, 2024). "Lastly, we report a great number of cases harbouring MT-RNR1 mutations associated with deafness after aminoglycoside therapy." (PMID 34680984, 2021). "Twenty-four cases were homoplasmic variants in MT-RNR1 who had a risk of deafness induced by ototoxic drugs, also had high-risk factors of pregnancy." (PMID 34276761, 2021). "The neonatal deafness gene tests showed two cases with 1555A>G mutation and two cases with 1494C>T mutation of the MTRNR1 gene." (PMID 24348793, 2014). "Three genetically unrelated subjects harboured the homoplasmic A1555G mutation in the MT-RNR1 gene, a mtDNA variant that has been associated with deafness." (PMID 23969527, 2013). "A certain range of mutations in the mt-RNR1 gene (A1555G, C1494T, T961G) was found to be associated with aminoglycoside-induced deafness." (PMID 22567152, 2012). "Using this method, the DFNM1 locus, a modifier of DFNB26-linked deafness was identified and the deafness phenotype associated with the 1555A>G mutation in MTRNR1 was shown to be modified by three different genes: MTO1, TFB1M and GTPBP3." (PMID 21119891, 2010). "Additionally, our patient was found to have a hotspot mutation at chrM:1494 in the mitochondrial MT-RNR1 gene, which can lead to aminoglycoside-induced deafness." (PMID 39113684, 2024). "Therefore, also pathogenic nucleotide substitutions in human MT-RNR1 are relatively rare, and mostly associate with deafness." (PMID 39261587, 2024). "Similarly, next-generation whole-exome sequencing analysis of many patients presenting with maternally inherited deafness have been found to have mutations in mt-RNR1, which encodes the 12S rRNA." (PMID 28752201, 2018). "In addition to GJB2, SLC26A4 and MT-RNR1, a variety of less commonly screened deafness genes accounted for a significant portion of genetic causes of non-syndromic deafness." (PMID 23767834, 2013). "Though definite mitochondrial point mutations and large deletions usually lead to syndromic deafness, some point mutations, notably in mt-RNR1 and mt-TS1 (tRNASer) genes, may cause SNHL." (PMID 22567152, 2012). "The MT-RNR1 gene mutations 1095 T>C and 1494 C>T also play a role in conditioning the development of AG-associated hearing loss, even if the frequency of these genetic variants in the general population and in patients with AG-related deafness is lower than that found for the 1555 A>G variation." (PMID 38543117, 2024). "In Taiwan, common deafness-associated genes include GJB2, SLC26A4, OTOF, MYO15A, and MTRNR1, which were similar to those found in other populations." (PMID 40943139, 2025). "In Taiwan, the common deafness-associated genes assessed, in order of prevalence included GJB2, SLC26A4, OTOF, MYO15A, and MT-RNR1." (PMID 38840095, 2024). "A total of 50 of 116 patients (43.1%) carried at least one genetic deafness-associated variant (one patient had mutations in both GJB3 and MT-RNR1)." (PMID 38172427, 2024). "In China, approximately 70% of hereditary deafness originates from four common deafness-causing genes: GJB2, SLC26A4, GJB3, and MT-RNR1." (PMID 38172427, 2024).
deafness (continued). "In this study, we characterized the clinical features of 12 Chinese Han deaf families in which mutations in common deafness genes GJB2, SLC26A4, and MT‐RNR1 were excluded." (PMID 32048449, 2020). "In this light, we recruited a series of Chinese Han deaf families that were preexcluded from mutations in common deafness genes GJB2,SLC26A4, and MT‐RNR1." (PMID 32048449, 2020). "The 12 Chinese probands have been previously excluded for mutations in common deafness genes GJB2,SLC26A4, and MT‐RNR1 by Sanger sequencing." (PMID 32048449, 2020). "Common deafness-associated genes in Taiwanese families, in order of prevalence, included GJB2, SLC26A4, OTOF, MYO15A, and MTRNR1, which are similar to those found in other populations." (PMID 31581539, 2019). "Common deafness-associated genes in the Taiwanese patients assessed, in the order of prevalence, included GJB2, SLC26A4, OTOF, MYO15A, and MTRNR1, which were similar to those found in other populations." (PMID 31581539, 2019). "From the epidemiological perspective, mutations of three deafness genes: GJB2, SLC26A4, and MT-RNR1, are much more prevalent than those of other genes worldwide." (PMID 30576380, 2018). "In this present study we have used an allele-specific PCR-based universal array designed to simultaneously screen nine deafness associated variants in the GJB2, GJB6, SLC26A4, MT-RNR1 and MTTS genes that are common in patients of European descent." (PMID 28273078, 2017). "Using this strategy, mutations in the rare deafness genes can be detected in between 23.2% and 62.5% of deaf patients that were excluded from mutations in GJB2, SLC26A or MT-RNR1." (PMID 26011067, 2015). "Our previous study performed mutation screening of common deafness genes GJB2, SLC26A4 and MT-RNR1 in seven consanguineous Uyghur families and detected bi-allelic SLC26A4 mutations in three of them." (PMID 26011067, 2015). "Bi-allelic GJB2 mutations were reported in 19.1% of patients with non-syndromic deafness, followed by bi-allelic SLC26A4 mutations in 12.1% and the mitochondrial MT-RNR1 mutations in 1.6%." (PMID 26011067, 2015). "In this study, we investigated the genetic etiology of nonsyndromic deafness in four consanguineous and two multiplex Uyghur families in which mutations in common deafness genes GJB2, SLC26A4 and MT-RNR1 were excluded." (PMID 26011067, 2015). "Cord blood was used for the screening of deafness-susceptibility genes, namely the GJB2, SLC26A4 and mitochondrial 12S rRNA (MTRNR1) genes." (PMID 24348793, 2014). "Pre-screening of mutations in three common deafness genes, GJB2, SLC26A4 and MT-RNR1, was performed in all 190 deaf probands by Sanger sequencing." (PMID 23767834, 2013). "We focused on the presumably rare deafness genes by pre-exclusion of mutations in three commonly screened deafness genes GJB2, SLC26A4 and MT-RNR1." (PMID 23767834, 2013). "Probands with mutations in commonly screened deafness genes GJB2, SLC26A4 and MT-RNR1 were pre-excluded by Sanger sequencing." (PMID 23767834, 2013). "Compared with 20 variants in the four genes of traditional testing, the positive rate of expanded screening in 159 variants of 22 deafness related genes increased significantly (65.2% on average), including GJB2 increasing by 97.2%, SLC26A4 by 21%, and MT-RNR1 by 150%." (PMID 34276761, 2021). "Next, target genomic capturing and next-generation sequencing for a panel of 127 genes related to hereditary hearing loss, which included the GJB2, GJB6, SLC26A, MTRNR1, and MTTS1 genes, were conducted to screen for the causative gene variant (s) of deafness in this family." (PMID 30068307, 2018). "Some mtDNA variants, in particular in the MT-RNR1 and tRNASer(UCN) genes, have been identified in several cases as the main cause of SNHL, suggesting that these two loci in particular are hotspots for deafness-associated mutations." (PMID 23969527, 2013).
deafness (continued). "A novel sporadic mutation in 12S rRNA (MT-RNR1), not previously reported in the literature, was found in a case of possible aminoglycoside-induced progressive deafness." (PMID 23969527, 2013). "Here, we analyzed clinical and molecular data from 21 Chinese deaf families who did not have hotspot mutations in the common deafness genes GJB2, SLC26A4, GJB3, and MT‐RNR1." (PMID 33095980, 2020). "We performed target region capture and next generation sequencing of 127 known deafness-related genes because the individual tested negative for hotspot variants in the GJB2, GJB3, SLC26A4, and MTRNR1 genes." (PMID 30068307, 2018). "Thus, through this analysis, the molecular etiology of deafness was confirmed in 23.56% (90/382) of the patients, and it involved the GJB2, SLC26A4, CDH23, MYO15A, and MT-RNR1 genes." (PMID 27018795, 2016). "A preliminary survey of Chinese domestic genetic epidemiology for deafness showed that the GJB2, SLC26A4 and mitochondrial 12S rRNA (MTRNR1) genes are common mutation hot spots in Chinese nonsyndromic hearing loss." (PMID 24348793, 2014). "Another study used a comprehensive deafness gene panel (including 50 non-syndromic and 7 non-syndromic/syndromic deafness genes) to screen 125 deaf probands without common mutations in GJB2, SLC26A4, or MT-RNR1, and found potentially causative mutations in 26.4% (33/125) of the patients." (PMID 30682115, 2019).
hearing loss (20 papers, 2013 to 2025). "Establishing a causal link between MT-RNR1 mutations and aminoglycoside-induced hearing loss is challenging due to limited data." (PMID 38840095, 2024). "We found that the presence of mtDNA pathogenic variants in the MT-RNR1 is associated with a higher risk of hearing loss, especially in the younger population (The age of 35 to 54)." (PMID 38840095, 2024). "Molecular epidemiological studies in China have identified several common deafness genes, such as GJB2, SLC26A4, and MT-RNR1, which account for 30%–50% of congenital hearing loss cases." (PMID 36568381, 2022). "Variants in the mitochondrial gene MT-RNR1 can lead to genetic susceptibility to aminoglycoside-induced hearing loss." (PMID 34276761, 2021). "Nonsyndromic hearing loss is an important cause for hereditary hearing loss, which has several different patterns of inheritance, in which mitochondrial mutations including m.1494C > T and m.1555A > G in the MTRNR1 gene are maternally inherited." (PMID 33510775, 2020). "For instance, the A1555G mutation in the MTRNR1 gene encoding 12S rRNA has been shown to dramatically predispose patients to hearing loss after exposure to aminoglycoside antibiotics." (PMID 30596476, 2018). "We developed a PCR-reverse dot blot (RDB) assay for screening 20 hotspot mutations of GJB2, GJB3, SLC26A4, and MT-RNR1, which are common non-syndromic hearing loss (NSHL)–associated genes in the Chinese population." (PMID 28505178, 2017). "Hence, this study was performed to explore the association between MT-RNR1 gene mutations and the risk of hearing impairment in the Taiwanese adult patients." (PMID 38840095, 2024). "Furthermore, 1148 cases harboured mutations in the MT-RNR1 gene, which are associated with aminoglycoside ototoxicity and/or non-syndromic hearing loss (464 were paediatric patients, 366 adults, and in 318 cases no age was documented)." (PMID 34680984, 2021). "MT-RNR1 is a mitochondrial gene associated with aminoglycoside-induced hearing loss." (PMID 33639928, 2021). "MT-RNR1 and MTTL1 variants lead to mitochondrial hearing loss, which has variable penetrance and severity, even within families." (PMID 36847978, 2023). "This is because there are hotspot genes and variants in the Chinese hearing loss population, such as GJB2 c.235del, SLC26A4 c.919-2A>G, and MT-RNR1 m.1555A>G." (PMID 36568381, 2022). "The GJB2, SLC26A4, MT-RNR1 and MT-TS1 genes have been reported as major pathogenic genes in nonsyndromic hearing loss." (PMID 28225033, 2017). "The GJB2, MT-RNR1, and SLC26A4 genes have been reported as common causative genes of hearing loss in the Korean population and some mutations of these genes are the most common mutations associated with hearing loss." (PMID 23469187, 2013). "Reverse dot blotting for 16 hotspot variants in the GJB2, GJB3, SLC26A4, and MTRNR1 genes was performed to rule out common variants in hereditary hearing loss." (PMID 30068307, 2018). "As an example, we discovered in our clinical center the m.1555G>A variant in the MT-RNR1, responsible for the amino-glycoside-induced and non-syndromic hearing loss in a family with isolated optic atrophy but without hearing impairment." (PMID 30619459, 2018). "In a large genetic study conducted in Taiwan on hereditary hearing loss, researchers initially ruled out variants of the connexin 26 gene and the 1555A > G variant of the MTRNR1 gene, subsequently finding 5 out of 86 cases with pathogenic variants of the KCNQ4 gene." (PMID 40178561, 2025). "Among the array of genes identified for non-syndromic hearing impairment to date, GJB2, SLC26A4, and the mitochondrial 12S rRNA (MT-RNR1) gene are much more prevalent than others across different populations." (PMID 38840095, 2024). "It is reported that MT-RNR1 m.1555A>G variant may lead to low or non-penetrance hearing loss." (PMID 36568381, 2022).
Obesity (16 papers, 2018 to 2025). Accumulation of substantial excess body fat. "The MT-RNR1 gene encodes MOTS-C protein that regulates insulin sensitivity and metabolic homeostasis and plays a protective role against diet-induced obesity." (PMID 33659027, 2021). "Additionally, two variants (MT:750G>A and MT:153A>G) were found to positively correlate with obesity risk, and one variant (MT:1243T>C) was exclusively found in the obese group within the MT-RNR1 gene, which encodes the MOTS-C protein known for promoting metabolic homeostasis and obesity reduction." (PMID 39464187, 2024).
diabetes (14 papers, 2021 to 2025). "Among these, the MT-RNR1 gene contains the sequence for mitochondrial open-reading frame of the 12 S rRNA-c (MOTS-c), one of mitochondrial-derived peptides (MDPs), reported to possess metabolic protective properties in various models of metabolic dysfunction, such as diabetes mellitus." (PMID 38840095, 2024).
hepatocellular carcinoma (4 papers, 2021 to 2025). A malignant tumor that arises from hepatocytes. "The transcripts encoded by MT-RNR1/2 genes have been associated with hepatocellular carcinoma and triple negative breast cancer progression." (PMID 40374694, 2025). "Furthermore, the polymorphism of this gene, MT-RNR1 G709A, has been associated with poor prognosis and is considered an important risk factor in patients with hepatocellular carcinoma." (PMID 39802950, 2024). "SNP presence on two noncoding genes (MT-RNR1 and MT-RNR2) encoded by mitochondrial DNA, mainly responsible for mitochondrial protein synthesis, were found to act as prognostic markers especially in hepatocellular carcinoma; the poor prognosis of HCC is largely due to high rates of tumor metastasis." (PMID 36832301, 2023).
nonsyndromic hearing loss (2 papers, 2022 to 2024). "The MT-RNR1 m.1192C>T mutation was associated with nonsyndromic hearing loss (DEAF), based on the MitoMaster database." (PMID 38990956, 2024). "MT-RNR1 is definitively associated with maternally inherited, aminoglycoside-induced hearing loss, and MT-TS1 is definitively associated with mitochondrial nonsyndromic hearing loss." (PMID 35571039, 2022).
Q fever (2 papers, 2019 to 2021). A bacterial infection caused by Coxiella burnetii. "QFS patients, CFS patients, and, to a lesser extent, asymptomatic Q fever seropositive controls showed a decreased expression of MDP-coding genes MT-RNR1 and MT-RNR2, resulting in a decreased production of humanin (MT-RNR2), compared to healthy controls." (PMID 31088495, 2019). "The expression of mitochondrial-derived peptide (MDP)-coding genes MT-RNR1 (MOTS-c) and MT-RNR2 (humanin) are decreased in CFS, QFS and to a lesser extent in Q fever seropositive controls, resulting in a decreased production of humanin." (PMID 34640355, 2021). "It is intriguing that MT-RNR1 and MT-RNR2 were less expressed in asymptomatic Q fever seropositive controls, albeit to a lesser extent than in QFS and CFS patients." (PMID 31088495, 2019). "Expression of MDP-coding genes MT-RNR1 (MOTS-c) and MT-RNR2 (humanin) is decreased in CFS, QFS, and, to a lesser extent, in Q fever seropositive controls, resulting in a decreased production of humanin." (PMID 31088495, 2019).
sensorineural hearing loss (2 papers, 2019 to 2025). "A 2007 study of Taiwanese families with sensorineural hearing loss reported that 3.2% carried the MTRNR1 m.1555A > G mutation, with additional family members also affected." (PMID 41329681, 2025). "Mutations in 12S rRNA (MT-RNR1), a component of the small subunit of the mitochondrial ribosome, have been associated with sensorineural hearing loss." (PMID 31835862, 2019).
chronic periodontitis (1 paper, 2025). A chronic inflammatory process that affects the tissues that surround and support the teeth. "Among the most highly upregulated genes in periodontitis were MT-RNR1 (Log2FC=4.3), MTRNR2L12 (Log2FC=3.9), pseudogenes, lncRNAs, and immunoglobulins (Ig)." (PMID 41124422, 2025).
COVID-19 (1 paper, 2023). A disease caused by infection with severe acute respiratory syndrome coronavirus 2. "The screening included alpha-globin 5′UTR and AES and mtRNR1 3′UTR that were previously used in the BioNTech-Pfizer COVID-19 vaccine and are known to contain motifs that increase the translation and stability of mRNA." (PMID 37371829, 2023).